IGF1 (insulin like growth factor 1)
Diseases named in the same sentence as IGF1 in open-access papers (continued):
Sharing a sentence is not in itself a finding about the gene and the disease.
Hypertension (continued). "Furthermore, the included studies reported that exercise training increased the levels of Bcl-2, Akt, p-Akt, PI3K, p-PI3K, IGF-1, and HSP 72 cardiac tissue in hypertension, suggesting that exercise training increases the chances of cell survival in the cardiac tissue to counteract hypertension." (PMID 37187789, 2023). "Indeed, studies show that patients with hypertension have higher IGF-1 levels than those without." (PMID 34078313, 2021). "One study observed that the protein level of IGF-1 was reduced in the non-exercise SHR group, whereas exercise training increased its level of hypertension." (PMID 37187789, 2023). "However, there are no data on IGF-1/IGF-1R expression in PH children/adolescents, presenting early stages of hypertension development in humans." (PMID 38540997, 2024).
colon carcinoma (143 papers, 2004 to 2025). "Overexpression of IGF-1 has been linked to an increased risk of colon cancer, and IGF-1 has been shown to stimulate the growth of the colon cancer cell lines HT-29 and SW-480." (PMID 36293321, 2022). "In agreement with the mitogenic and pro-survival roles of IGF1, studies have shown that elevated levels of IGF1 correlate with an increased risk of developing a number of tumors, including breast, prostate, and colon cancers." (PMID 35626664, 2022). "In support, using public databases showed that increased IGF1 expression was significantly associated with a poorer prognosis in patients with colon cancer." (PMID 30257507, 2018). "The increased risk of colon cancer among females who carried the risk allele can be explained by the increased levels of circulating IGF-1, which can promote cancer cell growth and inhibit apoptosis." (PMID 29484135, 2018). "Analysis from a cohort of colon cancer patients (GSE17536 series) using PrognoScan software showed that higher IGF1 expression in the patients was significantly associated with shorter survival." (PMID 30257507, 2018). "The studies of effects of rhIGF-1 on growth on CD have not been described yet, partly because of the theoretical risk of colon cancer in patients with high levels of circulating IGF-1." (PMID 27965886, 2016). "They showed a higher risk of colon cancer for those with IGF‐1 levels in the third (137–174 ng/mL) and fourth quartiles (IGF‐1 > 174 ng/mL) as compared to the controls (OR of 2.2 and 1.8, respectively)." (PMID 27734632, 2016). "High circulating levels of IGF-1 have been associated with increased risk of prostate, breast, and colon cancers." (PMID 25424625, 2014). "Individuals with higher than normal circulating levels of IGF-1 have an elevated risk of developing breast, prostate, lung, and colon cancers." (PMID 24458261, 2014). "Mechanistically, hypo-adiponectinaemia and possibly raised IGF-1 levels might drive the WHRadjBMI-colon cancer risk connection." (PMID 36558416, 2022). "High glycemic index diets, which chronically raise post-prandial blood glucose, may at least in part increase colon cancer risk via the insulin/insulin-like growth factor 1 (IGF-1) signaling pathway." (PMID 34208601, 2021). "Previous studies showed an association between elevated IGF-1 and the risks of colon cancer." (PMID 26901856, 2016). "The authors commented that this may be due to rectal cancer presenting at an earlier stage than colon cancer, which may have masked the association with IGF‐1 levels." (PMID 27734632, 2016). "In addition, human studies have established the positive association between IGF-1 levels and colon cancer risk." (PMID 24732966, 2014). "Since MMP-2, -7 and -9 have been associated with different aspects of colon cancer, we assessed whether IGF-1 and PPP could affect their protein expression in the HT-29 cell line." (PMID 22159423, 2012). "When we examined the literature, we found that IGF1 has previously been associated with proliferation and apoptosis, and it has also been demonstrated to play a crucial role in cholangiocarcinoma, colon cancer, kidney cancer, lung squamous cell carcinoma and liver hepatocellular carcinoma." (PMID 28178311, 2017). "Near-infrared-emitting AuNPs have been found useful in investigating mechano-growth factor (MGF), an insulin-like growth factor (IGF)-1 that is overexpressed in colon cancer tissues." (PMID 40650240, 2025). "Neutralizing IGF1 with an antibody significantly reduced the number of colonies formed by colon cancer cells." (PMID 40659611, 2025). "IGF-1 has been identified as playing a crucial role in enhancing the motility of breast and colon cancer cells." (PMID 39638246, 2024).
colon carcinoma (continued). "This was later linked to changes in insulin growth factor 1 (IGF1) signalling, which is regulated by PKC-βII in colon cancer." (PMID 38891113, 2024). "One of the mechanisms involves GLP-2 induced colon tumor promotion by stimulating insulin-like growth factor 1 (IGF-1) synthesis in intestinal subepithelial fibroblasts and its (GLP-2) own synthesis." (PMID 37076536, 2023). "A study conducted on HT29 colon cancer cells has shown that IGF-1 stimulates the PI3-K activity which further induces Akt phosphorylation." (PMID 37076536, 2023). "Several risk factors including hormones like insulin and insulin like growth factors (e.g., IGF-1) have been considered responsible for growth and progression of colon cancer." (PMID 37560308, 2023). "Simvastatin prompts the apoptosis of human colon cancer cells and inhibits IGF-1-induced ERK and Akt expression via the downregulation of IGF-1R expression and pro-apoptotic ERK activity." (PMID 37760764, 2023). "Insulin and IGF-1 have significant implications in colon cancer development, as they activate the phosphatidylinositol 3-kinase (PI3K)/Akt signaling pathway, stimulating cell growth and cell cycle signaling." (PMID 37835359, 2023). "In inflammation-related tumor models, inhibition of IGF1 signaling can reduce the number and size of colon tumors in wild-type mice." (PMID 35733095, 2022). "Of special note, two key marker genes, GREM1, and IGF1, were significantly differently expressed in 20 pairs of colon cancer and paracancerous tissues." (PMID 35910200, 2022). "The IGF-1 axis plays a vital role in carcinogenesis by promoting cellular turnover, leading to the accumulation of molecular alterations that influence colon carcinoma development." (PMID 34987906, 2021). "As shown in the interaction network, immune-related gene PLCG2 and IGF1, which are up-regulated in colon tumor samples, have significantly strong correlation with several TFs: FOXP3, IKZF1, CBX7, LMO2, MEF2C, EPAS1 and MAF." (PMID 33996273, 2021). "As a result, a marked induction of phospho-AKT was detected in the IGF-1 (insulin-like growth factor-1)-treated colon cancer cells." (PMID 34361052, 2021). "MiR-133a is also able to inhibit cellular proliferation and colony formation by targeting SP1 protein that binds to IGF1-R promoter blocking IGF-1 involved in colon cancer progression." (PMID 34575979, 2021). "Focusing on these results, the effect of voglibose on cell proliferation by IGF-1 was examined using a human colon cancer cell line." (PMID 32210144, 2020). "Diet modification has also been shown to downregulate the IGF-1 signaling in other cancers including prostate, pancreatic and colon cancer thereby delaying their progression." (PMID 32211051, 2020). "It has been reported that IGF1 can stimulate VEGFA mRNA expression by stabilizing HIF1A protein in human colon cancer cell line HCT116." (PMID 32041892, 2020). "Taken together, the fact that palmitic acid found in the ASCex used hare has a significant role on regulating IGF-1 or its receptors and subsequently enhances the chemopreventive activity of ASCex against colon cancer is highly suggested." (PMID 32986376, 2020). "Insulin and IGF-1 are leading determinants of proliferation and apoptosis and therefore likely to influence colon cancer growth and tumorigenesis." (PMID 33346251, 2020). "In an animal study of 1,2-dimethylhydrazine-induced colon cancer, it was found that the expression of IGF-1 is increased, and metformin downregulates IGF-1 and suppresses tumor angiogenesis." (PMID 31331111, 2019). "The other genes belong to metabolic pathways are GAPDH, INS, IGF1 which play significant role in proliferation and apoptosis in colon cancer." (PMID 30774816, 2018). "We found that DB treatment significantly suppressed IGF1-induced, CSC-associated properties, and acted synergistically with 5-FU to inhibit colon cancer proliferation." (PMID 30257507, 2018).
colon carcinoma (continued). "The results indicated that inhibition of IGF‐1 signaling reduced the colon tumor numbers in WT mice to similar levels as in p38α‐ΔMC mice." (PMID 29907597, 2018). "In this study, we examined the potential inhibitory effect of DB using 5-FU resistant colon cancer cells, induced by IGF1." (PMID 30257507, 2018). "Similar to p38α‐ΔMC mice, IGF‐1‐ΔMC mice showed a decreased number of colon tumors compared to WT mice, with less tumors larger than 4 mm and no tumors larger than 6 mm." (PMID 29907597, 2018). "We also show a correlation between IGF‐1 pathway activation and the infiltration of myeloid cells with active p38α in colon samples from patients with ulcerative colitis or colon cancer." (PMID 29907597, 2018). "To add support to our in vitro and in vivo results, we analyzed the public databases and demonstrated that the IGF1 mRNA level was significantly higher in patients with colon cancer." (PMID 30257507, 2018). "Colon cancer cells were co-cultured with adipocytes for 48 h and subsequently washed and subjected to Transwell migration assays using IGF-1 as the chemoattractant." (PMID 28151470, 2017). "Increased insulin and IGF-1 levels, together with decreased adiponectin levels, are also involved in the development of colon cancer." (PMID 29036907, 2017). "Transgenic mouse with deletion in liver-specific IGF-1 that result 75 % reduction in circulating IGF-1 exhibit reduction in development of colon cancer and reduced growth tumor xenografts." (PMID 27405474, 2016). "Insulin and IGF-1 alone or together elevated proliferation and reduced apoptosis in colon cancer MC38 cells." (PMID 26901856, 2016). "The correlation between insulin or IGF-1 and the risks of colon cancer in patients with T2DM is accepted widely." (PMID 26901856, 2016). "In this study, we investigated the effects and mechanisms of insulin and IGF-1 in colon cancer development in vitro and in vivo." (PMID 26901856, 2016). "In conclusion, our study suggests that the activation of ERK1/2 and JNK MAPK signaling by insulin and IGF-1, at least in part, is responsible for the development of colon cancer with T2DM." (PMID 26901856, 2016). "In conclusion, our results suggest that inhibition of the EGFR signaling pathway in colon cancer cells alters cytokine secretion (e.g. IGF-1) and prevents M1- to M2-like polarization in macrophages, thus inhibiting cancer cell growth." (PMID 27683110, 2016). "We found that the combination of insulin and IGF-1 significantly promoted the growth and the cell cycle of murine colon cancer MC38 cells than single use of insulin or IGF-1 in vitro." (PMID 26901856, 2016). "p65 knockdown reduces the basal level of MAT2A expression and blocks the additive effect of IGF-1 on MAT2A in human colon cancer cells." (PMID 26418898, 2016). "Overall, these results demonstrate that IGF-1 from colon cancer cells induced M2 macrophage polarization, and inhibition of EGFR in HCT116 cells reduced both IGF-1 secretion and HCT116 CM-induced macrophage polarization." (PMID 27683110, 2016). "This study was aimed to determine the mechanism of insulin/IGF-1 in colon cancer growth within a T2DM environment." (PMID 26901856, 2016). "In the present study, we observed that insulin and IGF-1, act as mitogens of colon cancer cells, activate the ERK1/2 and JNK MAPK signaling, resulting in cell cycle acceleration, cell growth and anti-apoptosis in colon cancer MC38 cells." (PMID 26901856, 2016). "Here we show that rapamycin inhibits the basal and IGF-1 stimulated adhesion of tumor cells derived from human rhabdomyosarcoma (Rh30), Ewing sarcoma (Rh1), colon carcinoma (HT29) and cervical adenocarcinoma (HeLa)." (PMID 25762619, 2015). "The association between high levels of insulin and insulin-like growth factor-1 (IGF-1) and the risk of colon cancer has also been demonstrated." (PMID 26082438, 2015).
colon carcinoma (continued). "Lowering the levels of circulating IGF1 in mice has been shown to inhibit the growth of colon cancer xenografts and there is reduced incidence of metastatic spread to the liver." (PMID 25699021, 2015). "Colon tumors were counted, and cytokines, insulin-like growth factor 1 (IGF-1), IGF binding protein 3 (IGFBP-3), adipokines, proliferation, apoptosis, and expression of microRNAs (miRs) were measured." (PMID 24732966, 2014). "In vitro studies demonstrated evidence of decreased cell growth following treatment with BIIB022 in lung, pancreas and colon cancer cell lines in the presence of IGF-1 or IGF-2 in culture media." (PMID 24458261, 2014). "Insulin, IGF-1, and IGFBP-3 have also been linked with colon cancer in both in vitro and in vivo studies." (PMID 24732966, 2014). "Relative to controls, DIO increased (and CR decreased) the number of colon tumors (p = 0.01), cytokines (p<0.001), IGF-1 (p = 0.01), and proliferation (p<0.001)." (PMID 24732966, 2014). "The signaling behind S1P-evoked HIF-1α also resembles IGF-1-induced HIF-1α expression in colon cancer cells and angiotensin II-evoked HIF-1α expression in vascular smooth muscle cells." (PMID 23824493, 2013). "We characterized insulin and IGF-1 receptor expression and the response to treatment with insulin, X10 and IGF-1 in the murine colon cancer cell line (MC38 cells) in vitro and in vivo." (PMID 24260289, 2013). "Both survivin and IGF-1 play important roles in inhibiting the mitochondria-mediated pathway that results in inhibition of apoptosis and prolonged survival of colon cancer cells." (PMID 23975167, 2013). "Proteomic analysis revealed that the cytoskeleton remodeling pathway is one of the critical pathways (4th) altered in the HT-29 colon cancer cells treated with RSV or IGF-1." (PMID 21849056, 2011). "Several but not all prospective studies have found evidence for a positive association between higher levels of IGF-1 or the molar ratio of IGF-1 and its primary binding protein, IGF-binding protein 3 (IGF-1/IGFBP-3 ratio) and colorectal and/or colon cancers." (PMID 22216097, 2011). "To identify important targets of RSV, we analyzed whole protein fractions from HT-29 advanced human colon cancer cell line treated with solvent control, IGF-1 (10 nM) and RSV (150 μM) using LC/MS/MS-Mud PIT (Multidimensional Protein Identification Technology)." (PMID 21849056, 2011). "The colon cancer cell number in the combination of IGF-1 and resveratrol treatment was similar to resveratrol treatment alone." (PMID 20504360, 2010). "Our results demonstrated that resveratrol suppresses the colon cancer cell proliferation even when the cells are primed to proliferate with IGF-1." (PMID 20504360, 2010). "Growth stimulatory effects of IGF-1 and the anti-proliferative effects of resveratrol were investigated using HT-29 and SW-480 colon cancer cells." (PMID 20504360, 2010). "IGF-1 treatment elevated pAkt, pGSK3β, and cyclin D1 levels resulting in augmented proliferation of HT-29 colon cancer cells." (PMID 20504360, 2010). "The IGF pathway has been linked to colorectal malignancy, and serum levels of IGF1 have been associated with colon cancer risk." (PMID 20034393, 2009). "This is in line with observations from other groups showing that IGF-1-induced VEGF expression in colon cancer cells and fibroblasts occurs through the MEK/ERK pathway." (PMID 14997210, 2004). "However, the controversy in this case centers on MDA-9/Syntenin, as it appears to control invasion rather than participate in proliferation Another non-canonical pathway involves the kinase PKA, which participates in IGF-1 signaling in colon cancer." (PMID 39638246, 2024). "Moreover, studies indicated that insulin and IGF-1 can enhance the proliferation of colon cancer cells and facilitate the growth of colon cancer allografts in obese mice." (PMID 37835359, 2023).